GATA3 (GATA binding protein 3)
Diseases named in the same sentence as GATA3 in open-access papers (continued):
Sharing a sentence is not in itself a finding about the gene and the disease.
paraganglioma (19 papers, 2014 to 2025). A benign or malignant neoplasm arising from paraganglia located along the sympathetic or parasympathetic nerves. "Paraganglioma can be distinguished by immunohistochemical staining for GATA3 and stains for enzymes that synthesize catecholamines." (PMID 39055477, 2024). "UCa shares its GATA3 expression with NA and paraganglioma arising from the urinary tract, although GATA3 expression in CCAC of the urinary tract has not been evaluated." (PMID 36320040, 2022). "While calcitonin and CGRP can also be expressed in paragangliomas, the demonstration of tyrosine hydroxylase and GATA3 distinguishes paraganglioma from other neuroendocrine neoplasms." (PMID 32632840, 2020). "Despite GATA3 also being expressed in urothelial, renal, germ cell tumors, and paragangliomas, a positive expression in extramammary NEN has not been described." (PMID 32244940, 2020). "However, both WDNETs and paraganglioma also express chromogranin, and the cytokeratin expression in WDNWTs and GATA3 expression in paraganglioma also help differentiate these tumors from GLI1-rearranged enteric tumors." (PMID 39851545, 2025). "GATA3 immunoreactivity can be seen in paragangliomas or pheochromocytomas." (PMID 39568313, 2025). "Besides metastatic localization of GATA3-positive tumors in the nasal cavity, GATA3 expression may be seen in primary sinonasal neuroendocrine neoplasms, like ectopic pituitary neuroendocrine tumors/adenomas (PitNETs) and paraganglioma." (PMID 35522392, 2022). "The tumor cells showed positive staining for CKAE1/AE3, CK8/18, CK7, 34βE12, and GATA-3, while other antibodies were negative, excluding gastrointestinal stromal tumor, leiomyosarcoma, and paraganglioma." (PMID 40917856, 2025). "GATA3 is positive in paragangliomas and negative in PanNETs, while CKs are negative in paragangliomas and positive in PanNETs." (PMID 34647171, 2022). "For example, paraganglioma generally expresses GATA3 and tyrosine hydroxylase, while neurocytoma does not." (PMID 35663322, 2022). "A novel marker in the diagnosis of paragangliomas is GATA3 that is expressed in about 80% of all cases regardless of site." (PMID 24883221, 2014). "Additionally, the maxillary location and the negative staining for S100, SOX10, and GATA3 do not support a diagnosis of paraganglioma or olfactory neuroblastoma." (PMID 39404971, 2024). "Both paraganglioma and panNETs with paraganglioma-like morphology show S100-positive sustentacular cells complicating the differential diagnosis, which is mainly based on the lack of low weight cytokeratins positivity and GATA3, tyrosine hydroxylase, PHOX2B, and Hand2 expression in the former." (PMID 40668487, 2025). "In contrast to the PanNETs though, paragangliomas are negative for Keratins (e.g., AE1/AE3 or CAM5.2) or CEA with immunochemistry (as they are non-epithelial neoplasms), whereas they exhibit immunopositivity for GATA-3 and tyrosine hydroxylase (TH)." (PMID 36010170, 2022).
helminth infection (18 papers, 2017 to 2025). "On the other hand, the upregulation of GATA3 and IL-4 might suggest a concurrent Th2 response, which is typically associated with helminth infections and allergic reactions and may contribute to the modulation of Th1/Th17 inflammatory reactions." (PMID 39339863, 2024). "Similarly, helminth infection was associated with a significant upregulation of GATA3 expression in the lung tissue." (PMID 31673002, 2019). "In contrast, biotin− DCs from both helminth infections induced TN cells to differentiate towards a GATA3+ Th2 phenotype, in accordance with the in vivo findings of endogenous Th2 response to helminth infections." (PMID 39700315, 2025). "In vivo blockade of IL-10 signalling during helminth infection resulted in an expansion of IFNγ+ and Tbet+ Th1 cells in the small intestine and a coincident decrease in IL-13, IL-5 and GATA3 expression by intestinal T cells." (PMID 35428872, 2022). "That a majority of 2W1S-specific CD4+ T cells in the lung express GATA3+ is consistent with the expected T cell phenotype during most helminth infections." (PMID 34237106, 2021). "IL-4Rα signaling is crucial for the accumulation of GATA3+ Tregs in the inflamed intestine during helminth infections; therefore we analyzed the Th2 cytokines IL-4, IL-5, and IL-13 secreted by LPMCs in the colon." (PMID 34336843, 2021). "It is believed that IL-4Rα signaling is crucial to up-regulate GATA3 in Tregs and promote the accumulation of GATA3+ Tregs in the inflamed intestine during helminth infection." (PMID 34336843, 2021). "The induction of GATA3+ Th2 cells is a prototypical host immune response to helminth infections and the Th1/Th2 ratio is supposed to be a crucial point in assessing the effects of helminth therapy on Th1-driven inflammatory conditions." (PMID 33572978, 2021). "The caveat with Gata3 is that ILC2s in the lungs are able to downregulate Gata3 expression under specific conditions such as viral, or helminth infections, however, under steady state conditions Gata3 is a reliable marker for pulmonary ILC2s." (PMID 31231357, 2019). "In addition, Rorafl/flIL7raCre mice also had a significantly (p < 0.05) reduced frequency of lung GATA3+CD4 Th2 cells after helminth infection, compared with infected Rorafl/fl mice." (PMID 37387671, 2023). "Th2 cells (CD4+GATA3+) defend against helminth infection and contribute to allergic inflammation." (PMID 34064626, 2021). "While GATA-3 expression is necessary for Treg stability under inflammatory conditions, RORγt+ Treg exhibit a highly activated phenotype and limit the Th2-driven control of helminth infection and immune pathology in intestinal inflammation." (PMID 30349532, 2018). "ILC2 express GATA binding protein-3 (Gata3), produce IL-13 and IL-5 in response to IL-25, IL-33, and thymic stromal lymphopoietin (TSLP) and contribute to the defense against helminthic infections as well as to the pathogenesis of allergic inflammation [1248]." (PMID 34910301, 2021). "Helminth infections are typically characterized by the activation and expansion of CD4+ T helper 2 (Th2) cells, which express the transcription factor GATA-3 and secrete interleukin (IL)-4, IL-5, IL-9, and IL-13, leading to IgG1 and IgE antibody production." (PMID 28791259, 2017). "Asking whether infections with S. ratti led to the expansion of Th2/1 cells as previously shown for other helminth infections, we screened the organs of naïve and infected mice for CD4+ T cells simultaneously expressing GATA-3 and T-bet." (PMID 28676845, 2017). "Furthermore, we have previously reported a subset of Th hybrid cells expressing both transcription factors T-bet and GATA-3, as well as producing IFN-γ and IL-4 at intermediate levels during helminth infections." (PMID 28791259, 2017).
liver cancer (18 papers, 2020 to 2025). An epithelial or non-epithelial malignant neoplasm that arises from the liver. "KIAA1429 [also named as Vir like M6A methyltransferase associated (VIRMA)] promotes liver cancer progression via m6A modification of the lncRNA GATA3." (PMID 32793593, 2020). "KIAA1429 has been indicated to drive the progression of liver cancer through the m6A modification of the lncRNA GATA3." (PMID 36277972, 2022). "Studies have found that KIAA1429 induced m6A methylation on the 3’UTR of GATA3 pre-mRNA, which led to the degradation of GATA3 pre-mRNA and promoted the progression and metastasis of liver cancer." (PMID 35945641, 2022). "M6A regulators are implicated in the progression of several tumors through the modification of certain lncRNAs, for instance, KIAA1429 enhanced the progression of liver cancer by m6A modification of the lncRNA GATA3." (PMID 35669515, 2022). "KIAA1429 facilitates the development of liver cancer through regulating the expression of GATA3 by m6A methylation modification." (PMID 36505780, 2022). "KIAA1429 facilitates liver cancer progression by regulating the expression of GATA3 through m6A methylation modification." (PMID 36505780, 2022). "The downstream effect of GATA3 m6A methylation was disrupted binding of HuR protein, down regulation of GATA3, and increased metastasis of liver cancer." (PMID 35368653, 2022). "KIAA1429 overexpression is seen in many types of cancer that drive tumor growth and liver cancer cells’ metastasis by targeting GATA3." (PMID 34332578, 2021). "GATA3 was identified as the direct downstream target of VIRMA-mediated m6A modification in liver cancer through the combination of immunoprecipitation sequencing (RIP-seq), and high-throughput methylated RNA immunoprecipitation sequencing (MeRIP-seq)." (PMID 33731118, 2021). "KIAA1429 preferentially induces the m6A modification of the 3ʹUTR of GATA3 pre-mRNA in liver cancer cells, isolates HuR, degrades GATA3 pre-mRNA, downregulates the expression of GATA3, and, hence, promotes cancer growth." (PMID 34858499, 2021). "After the disjunction of HuR and the downregulation of GATA3 pre-mRNA, KIAA1429 mediates m6A methylation on the 3′ UTR of GATA3 pre-mRNA in liver cancer cells guided by GATA3-AS." (PMID 32733931, 2020). "Certain studies show that KIAA1429 contributes to liver cancer progression through N6-methyladenosine-dependent post-transcriptional modification of GATA3 and regulates the migration and the invasion of HCC by altering the m6A modification of ID2 mRNA." (PMID 32903675, 2020). "In liver cancer, though its m6A modification function, KIAA1429 promotes cell proliferation and metastasis by GATA3." (PMID 40611274, 2025). "KIAA1429 mediates m6A of GATA-binding protein 3 (GATA3) that further regulates cell proliferation and metastasis in liver cancer." (PMID 37598390, 2023). "KIAA1429 is involved in liver cancer progression and regulates the invasion of HCC by altering the m6A modification of ID2 and GATA3." (PMID 32903675, 2020). "Therefore, VIRMA promote the growth, metastasis and malignant phenotypes of liver cancer cells by regulating the GATA expression, which is mediated by the m6A modification of GATA3 pre-mRNA." (PMID 33731118, 2021).
autoimmune disease (17 papers, 2012 to 2025). A disorder resulting from loss of function or tissue destruction of an organ or multiple organs, arising from humoral or cellular immune responses of the individual to their own tissue constituents. "GATA3 is a risk locus associated with autoimmune disease, including rheumatoid arthritis; however, the link between protein-coding variants in GATA3 and autoimmune disease has not been well established." (PMID 41190486, 2025). "Conversely, the presence of impaired GATA3 is associated with a variety of diseases, including neurodegenerative diseases, autoimmune diseases, and cancers." (PMID 39768217, 2024). "GATA3 is an essential factor for immune tolerance, and its removal is associated with autoimmune diseases." (PMID 33585004, 2020). "The G allele (rs2232365) alters the binding site of the GATA3 factor and has been associated with a predisposition to autoimmune diseases." (PMID 32743104, 2020). "It is remarkable that two HDR patients with similar mutations in GATA3 both developed autoimmune disease, which suggests a shared mechanism." (PMID 31238969, 2019). "The identification of a second HDR patient with autoimmune disease with a similar mutation in GATA3 further supports the connection between GATA3 and autoimmune disease." (PMID 31238969, 2019). "Extension of GATA3 analysis to other autoimmune disease cohorts showed only association with alleles at a single SNP, rs3802604, in the New Zealand rheumatoid arthritis population, replicating a recent finding in a large multinational RA patient cohort." (PMID 24614117, 2014). "FOXP3 and GATA3 exert immune suppressive activity; however, some of their gene variants have been shown to impair immune-suppressive activity, thus contributing to the development of autoimmune diseases." (PMID 33806248, 2021). "According to the GWAS Catalog and Immunobase, five of these shared loci (PADI4 at 1p36.13, NAB1 at 2q32.3, COBL at 7p12.1, CCL21 at 9p13.3, and GATA3 at 10p14) have been associated with a single autoimmune disease so far and thus they represent new pleiotropic loci in autoimmunity." (PMID 30572963, 2018). "Further studies are needed to investigate the role of pathogenic variants in the GATA3 gene in the pathogenesis of JIA and other autoimmune diseases." (PMID 41190486, 2025). "MS is an autoimmune disorder described by altered Th-cell differentiation that is mainly driven by GATA3." (PMID 39768217, 2024). "In autoimmune diseases such as multiple sclerosis, abnormal GATA3 expression disrupts immune system balance, contributing to the autoimmune attack on the nervous system." (PMID 39768217, 2024). "XAV939 reduced the expression of T‐bet and GATA3, effectively, that is beneficial to maintain Th1/Th2 balance in patients with autoimmune disease." (PMID 38414312, 2024). "This discovery provides a new understanding of GATA3’s role in autoimmune diseases and potential therapeutic targets." (PMID 39768217, 2024). "The key transcription factors of T helper cell subpopulations, including T-bet, GATA3, RORγt, and Foxp3 are involved in various autoimmune diseases." (PMID 30254507, 2018). "Furthermore, GATA3 analysis helps uncover the shared genetic architecture between conditions like cancer and autoimmune diseases, guiding therapeutic interventions and disease management." (PMID 39768217, 2024). "Notably, GATA3 exhibits a dual function in both the progression and control of autoimmune diseases." (PMID 39768217, 2024). "Our data show that Gata3 had a tendency to be significantly decreased after silicone implantation, indicating imbalanced T helper cell differentiation that may give rise to Th1 autoimmune disease." (PMID 29245939, 2017). "STAT1 overexpression and GATA3 overexpression in FOXP3+ Tregs have been reported in autoimmune diseases." (PMID 38774869, 2024).
autoimmune disease (continued). "Four DEGs (SOD2, GATA3, PPARG, and MAPK14) were related to various functional categories, including “inflammatory response”, “cell activation”, “autoimmune disease”, and “vascular endothelial cell”." (PMID 34026343, 2021). "Gata3 (GATA Binding Protein 3) plays an indispensable role in Th2 differentiation, and its overexpression has been considered a therapeutic target in autoimmune disease." (PMID 29245939, 2017). "Among these markers, GATA3 and STAT5 play essential roles in generating IL‐4 during the process of Th2 polarization, and the production of IL‐4 can enhance Th2 polarization and augment GATA3 expression in autoimmune diseases." (PMID 32406154, 2020). "However, to the best of our knowledge, the DNA methylation dynamics of Tbx21, Gata3, Rorc, and Foxp3 during the development of autoimmune disease has not yet been studied and was therefore the subject of our study, whereby we chose uveitis as a disease model." (PMID 30254507, 2018).
invasive breast carcinoma (17 papers, 2006 to 2025). A carcinoma that infiltrates the breast parenchyma. "Remarkably, we discovered that different subtypes of genetic aberrations within a single cancer driver gene, such as PIK3CA or GATA3, are associated with opposite histologic changes in invasive breast cancer." (PMID 27283966, 2016). "Furthermore, we discovered that different types of genetic abnormalities (mutation versus amplification) within the same cancer driver gene (PIK3CA or GATA3) were associated with opposite histologic changes in invasive breast cancer." (PMID 27283966, 2016). "For example, PIK3CA and GATA3 genes may carry a mutation or amplification in invasive breast cancer." (PMID 27283966, 2016). "Low levels of GATA3 are associated with invasive breast carcinomas." (PMID 22369133, 2011). "Their diagnosis of primary invasive breast carcinomas was confirmed by GATA3 and estrogen receptor (ER) IHC." (PMID 40347269, 2025). "In silico analysis of the relationship between CTSV mRNA expression and GATA3 protein expression was also examined in clinical samples, using the TCGA 2012 breast invasive carcinoma dataset via cBioPortal." (PMID 33298139, 2020). "In the present study we could not find an association between GATA-3 expression and lymph node status, in agreement with a recent cohort study from Voduc and colleagues comprising more than 3,000 invasive breast cancers." (PMID 19549328, 2009). "We found that GATA3 expression was correlated with WISP1 and that GATA3 was up-regulated in invasive breast cancer compared to normal tissue." (PMID 24426833, 2014). "A small proportion of tumors (6%, 39 of 623) demonstrated positivity for mammaglobin and negativity for GATA3; the majority of them were categorized as invasive breast carcinomas of no special type (82%, 32 of 39)." (PMID 37306115, 2024). "Of the 7 invasive breast carcinomas of no special type, 2 were positive for GATA3, 2 were positive for SOX10, and 1 was positive for both GATA3 and SOX10." (PMID 37306115, 2024). "To validate the relationship of GATA3 and MUC1 in breast tissues further, we performed mRNA expression analyses of 36 invasive breast carcinomas by real-time RT-PCR, and protein expression analysis in 263 breast tissue samples by means of immunohistochemistry on TMAs." (PMID 17078870, 2006). "The invasive breast carcinoma of no special type demonstrated an in situ component, positivity for SOX10 and GATA3, and the patient had no other oncologic history." (PMID 37306115, 2024). "In our cohort of 633 TNBC tumors, a panel consisting of GATA3, mammaglobin and SOX10 similarly identified 96% of all TNBC and 97% of invasive breast carcinomas of no special type." (PMID 37306115, 2024).